APOA1 (apolipoprotein A1)
Diseases named in the same sentence as APOA1 in open-access papers (continued):
Sharing a sentence is not in itself a finding about the gene and the disease.
liver cirrhosis (3 papers, 2008 to 2024). "Recently, there has been a comprehensive report on circulating mRNA analysis, and among the mRNAs whose expression is different between HCC and liver cirrhosis and the mRNA in liver tissue used for this analysis, Alb, ApoA1, ApoA2, and Ftl was common with both study." (PMID 33303811, 2020).
mastitis (3 papers, 2020 to 2022). Inflammation of breast tissue during lactation or postpartum due to an obstructed duct or infection. "The immune-modulatory functions of APOA1 were also reported during S. uberis and S. aureus mastitis but to a lesser extent." (PMID 33260718, 2020). "A study using proteomics in bovine milk from mastitis cows, identified proteins involved in the immune response, including lactoferrin, transferrin, fibrinogen, apolipoprotein A1, glycosylation-dependent cell adhesion molecule-1, peptidoglycan recognition proteins, as well as cathelicidin-1." (PMID 36356101, 2022). "However, we found that APOA1, APOA4, APOE, and RBP4 were downregulated during clinical mastitis." (PMID 36335251, 2022).
memory impairment (3 papers, 2020 to 2025). "Moreover, ApoA1/ApoE KO mice showed increased plasma amyloid 1-42 levels and exacerbated memory impairment, suggesting an important role of more than one apolipoprotein in the clearance of amyloid 1-42 from the brain." (PMID 41516203, 2025).
meningitis (3 papers, 2015 to 2023). A disorder characterized by acute inflammation of the meninges of the brain and/or spinal cord. "Here, we report APOA5 to be associated with meningitis, while previous studies implicated various other apolipoproteins, such as APOA1 and APOE, are involved in meningitis, as well as various bacterial or respiratory infections, both in human and mouse studies." (PMID 37108169, 2023).
Miscarriage (3 papers, 2019 to 2024). A pregnancy that ends at a stage in which the fetus is incapable of surviving on its own, defined as the spontaneous loss of a fetus before the 22th week of pregnancy. "High expression levels of APOA1 serve as a biomarker for poor endometrial environment and as a measure of success in vitro-produced embryos, as 76% of early miscarriage cases had high APOA1 levels when compared to controls." (PMID 38927701, 2024). "Evidence has revealed that low APOA1 expression is critical for establishing pregnancy, and elevated APOA1 expression in chorionic villi correlates with early miscarriage, which is also characterized by impaired trophoblast invasion." (PMID 38003549, 2023). "As women with MeS show low levels of ApoA1, therefore lowering of ApoA1 isoforms in cases the history of miscarriage in our study imply a physiological interaction among common proteins leading to common protein expression patterns in both the diseases." (PMID 30783564, 2019). "Increased expression of TF, HP protein (three isoforms), SYNE 1, serpin 38, and ApoA1 in groups A, C, and D provides a better insights into the molecular link between the history of miscarriage and MeS." (PMID 30783564, 2019). "Networking analyses suggest cross talk between the four dysregulated proteins, that is, HP, TF, ApoA1, and TTR as a connecting link between miscarriage history and MeS." (PMID 30783564, 2019). "A cross talk between HP, ApoA1, TF, and TTR estabishs link between miscarriage and MeS." (PMID 30783564, 2019).
oesophageal cancer (3 papers, 2010 to 2024). "For oesophageal cancer, besides cystatin C and of White race, lower Apolipoprotein A1, higher monocyte count and lower ionized serum calcium were associated with higher risk of getting oesophageal cancer." (PMID 38263244, 2024).
polyneuropathy (3 papers, 2012 to 2025). A disease or disorder affecting more than one nerve. "Several studies have shown that the mutation in APOA1 is involved in the pathogenesis of polyneuropathy." (PMID 26337083, 2015).
renal clear cell carcinoma (3 papers, 2024 to 2025). "In patients with kidney clear cell carcinoma (KIRC), the expression levels of APOA1 mRNA in KIRC tissues were lower than those in para-cancerous and normal kidney tissues, and high expression of APOA1 mRNA in tissues was correlated with worse OS and disease-free survival." (PMID 38212711, 2024).
aortic aneurysm (2 papers, 2024 to 2026). A ruptured aneurysm located in the wall of the proximal portion of the descending aorta proceeding from the arch of the aorta. "In terms of aortic aneurysm, there was a significant positive association between the ApoB/ApoA1 ratio and the incidence rates of aortic aneurysm, especially AAA (all PFDR<0.05)." (PMID 38310324, 2024). "Our research has found that an increase in the ApoB/ApoA1 ratio was significantly related to the formation of aortic aneurysm." (PMID 38310324, 2024).
autoimmune encephalitis (2 papers, 2023 to 2024). Inflammation of the brain secondary to an immune response triggered by the body itself. "Clinical parallels have been identified, notably linking HDL cholesterol and ApoA1 status with the prognosis and exacerbation of autoimmune encephalitis." (PMID 39281610, 2024).
Cerebral ischemia (2 papers, 2023 to 2025). Restriction of arterial blood supply to the brain associated with insufficient oxygenation to support the metabolic requirements of the tissue. "Future studies should answer the question of whether ApoA1 may also be associated with short-term and long-term prognosis in patients after cerebral ischemia, and whether it may be a therapeutic target for preventing recurrent cerebral ischemia." (PMID 41516203, 2025). "In the cerebral ischemia model used, previous studies have shown increased staining of cortical neurons for ApoA1 during 7–30 days of survival, which currently correlates positively with gene expression." (PMID 41516203, 2025). "Our experimental studies showed the overexpression of ApoA1 in the frontal cortex 7–30 days and 1.5–2 years after an episode of cerebral ischemia." (PMID 41516203, 2025). "For example, ApoA1 is also of interest in the context of human cerebral ischemia, where it is seen as a promising biomarker as well as a potential therapeutic target." (PMID 41516203, 2025).
cholelithiasis (2 papers, 2021 to 2025). The presence of crystallized deposits forming in the gallbladder or biliary tree, primarily composed of cholesterol, bilirubin, and bile. "The negative mediation effects observed for the ratio of apolipoprotein B to apolipoprotein A1, phospholipid levels in VLDL, and triglyceride levels in large LDL and IDL suggest a complex interplay between lipid metabolism, BMI, and cholelithiasis risk." (PMID 39747165, 2025).
colorectal tumor (2 papers, 2009 to 2023). "APOA1, a major protein moiety in high-density lipoprotein (HDL) particles, may suppress colorectal tumor progression via regulating the metabolism of intracellular cholesterol." (PMID 36812479, 2023). "For example, Apoa1 (apolipoprotein A-I) is known to be the major protein moiety of high-density lipoprotein (HDL) and is mainly produced in the liver and the intestine but is also produced in vitro by some differentiated cell lines established from human colorectal tumors." (PMID 19529782, 2009).
congestive heart failure (2 papers, 2020 to 2023). Failure of the heart to pump a sufficient amount of blood to meet the needs of the body tissues, resulting in tissue congestion and edema. "Clinical trials have reported that BBR treatment reduced the levels of the cardiovascular risk indicators, such as LDL, and apolipoprotein B/apolipoprotein A1 (ApoB/ApoA1) ratios, and improved the quality of life in congestive heart failure patients in combination with conventional therapy." (PMID 32855766, 2020).
diabetic macular edema (2 papers, 2015 to 2022). "Also, in the vitreous of diabetic macular edema, APOA-4 and other pigment epithelium-derived factor, like APOA-4, APOA-1, trip-11, and RBP were elevated." (PMID 26608305, 2015).
diffuse large B-cell lymphoma (2 papers, 2022 to 2024). "However, the role of serum apolipoprotein A1 (ApoA1) in the prognosis of patients with diffuse large B-cell lymphoma (DLBCL) remains unclear." (PMID 38212711, 2024). "We conducted a clinical observational trial and found that HDL-C, ApoA1, TG, and e’ were independent influencing factors of anthracycline-induced subclinical cardiotoxicity (AISC) in diffuse large B-cell lymphoma (DLBCL) patients receiving 3 cycles of (R)-CHOP." (PMID 36115970, 2022).
E. coli infection (2 papers, 2018 to 2024). "Protein network analysis indicated that genes such as FOS, CTLA4, APOA1, CEL, FRK, and AGTR1 had the strongest association with other genes, highlighting their crucial roles in E. coli infection." (PMID 39707535, 2024). "A number of genes involved in fatty acid transport, such as fatty acid-binding protein 1 (Fabp1) and four apolipoproteins (Apoa1, 2, 5 and Apoc3), were downregulated by E. coli infection in Mkp-1+/+ mice." (PMID 30563203, 2018).
eosinophilia (2 papers, 2021 to 2022). "APOA1 and APOCs (APOC-II and APOC-III) results negatively correlated with peripheral eosinophilia (eosinophil % of circulating granulocytes)." (PMID 35453511, 2022). "In particular, we detected upregulation of certain protein species of APOA1, APOC-II, and APOC-III, which resulted as negatively correlated with peripheral eosinophilia (cell/mm3%) and upregulation of certain protein species of the antioxidants ceruloplasmin and transthyretin." (PMID 35453511, 2022).
falciparum malaria (2 papers, 2012 to 2025). "This study investigates the association between two APOA1 gene polymorphisms (G-75A and C+83T), APOA1 levels, and inflammatory markers (tumor necrosis factor-alpha and interleukin-6) in Nigerian children with uncomplicated Plasmodium falciparum malaria." (PMID 40061813, 2025).
gastric tumor (2 papers, 2023 to 2024). "A preclinical study showed that reduced plasma APOA1 level is associated with gastric tumor growth in mouse cancer xenograft model." (PMID 39606245, 2024). "APOA1 was identified at decreased levels in plasma from mice bearing larger gastric tumor xenografts compared to those with smaller tumors." (PMID 37999824, 2023).
glomerular disease (2 papers, 2019 to 2022). "When participating RTR were stratified according to anti-apoA-1 IgG seropositivity, there was again a significant association with a higher prevalence of previous MI (p = 0.02), glomerular disease (p = 0.03) and tubulo-interstitial disease (p = 0.03) as the primary renal disease." (PMID 31261925, 2019).
Glucose intolerance (2 papers, 2018 to 2021). Glucose intolerance (GI) can be defined as dysglycemia that comprises both prediabetes and diabetes. "Interestingly, only obese women of phenotype D show aggravated glucose intolerance as indicated by poorer 2 h glucose levels following OGTT, and significantly reduced ApoA-1 levels coupled with increased ApoB:ApoA1 ratios compared to lean counterparts." (PMID 33635862, 2021).
hepatitis B (2 papers, 2014 to 2021). "Other indicators for screening PC in patients with T2DM include BMI; age of T2DM onset; hepatitis B virus infection; and total bilirubin, alanine aminotransferase, creatinine, apolipoprotein A1, and leukocyte (WBC) levels." (PMID 34485159, 2021).
hypercoagulation (2 papers, 2024 to 2025). "In the logistic regression analysis of thrombophilia markers and gene polymorphisms in the patient and control groups, no statistically significant increase was observed in markers other than APOA1 rs5069 gene polymorphism." (PMID 39295604, 2024). "In the interpretation of thrombophilia markers and gene polymorphisms using logistic regression analysis in the patient and control groups, no statistically significant risk increase was observed for markers other than APOA1 rs5069 gene polymorphism." (PMID 39295604, 2024).
Hyperinsulinemia (2 papers, 2019 to 2023). An increased concentration of insulin in the blood. "Sealls and colleagues demonstrated that Cr3+ reversed hyperinsulinemia-induced cellular cholesterol accrual and associated defects in cholesterol transporter ABCA1 trafficking and apolipoprotein A1-mediated cholesterol efflux." (PMID 30723735, 2019).
hyperopia (2 papers, 2008 to 2017). A refractive error in which rays of light entering the eye parallel to the optic axis are brought to a focus behind the retina, as a result of the eyeball being too short from front to back. "Another link could be established to apolipoprotein A1 (ApoA-I), whose level was elevated in the retina after the development of hyperopia, and the LDL-receptor." (PMID 18769560, 2008).
infarction (2 papers, 2016 to 2020). A localised pathological necrosis of tissue resulting from obstruction of the blood supply usually by a thrombus, an embolus, or vascular torsion. "Our results suggested that various subtypes of AC-LAO have different susceptibility to different subtypes of infarction and outcomes, and further indicated that age promoted the progression of AC-LAO from single- to multiple-vessel occlusion, while ApoA1 suppressed this progression simultaneously." (PMID 32103113, 2020).
intrahepatic cholangiocarcinoma (2 papers, 2024 to 2025). A carcinoma that arises from the intrahepatic bile duct epithelium in any site of the intrahepatic biliary tree. "Serum ApoA1 level is an independent prognostic factor for OS in patients with CRC and advanced intrahepatic cholangiocarcinoma treated with PD-1." (PMID 38212711, 2024).
invasive breast carcinoma (2 papers, 2020). A carcinoma that infiltrates the breast parenchyma. "For invasive breast carcinoma, apolipoprotein A1 RNA expression did not seem to differ, whereas protein expression was decreased in tumor tissue." (PMID 32998735, 2020).
leishmaniasis (2 papers, 2025). Infectious disease that is transmitted through the bite of hematophagous female phlebotomine sand flies. "Although not statistically significant when comparing the different SGs in the present study, lower ApoA-1 concentrations were observed in dogs with acute B. canis infection, like in dogs with leishmaniasis." (PMID 41437958, 2025). "To understand the fate of ApoA1 in leishmaniasis, as a preliminary assessment, we quantified serum ApoA1 levels from VL and PKDL patients in comparison to healthy individuals." (PMID 41339683, 2025). "Overall, these results implicate ApoA1 as a vital immunomodulatory factor and potential therapeutic target in leishmaniasis." (PMID 41339683, 2025). "Significantly decreased ApoA-1 concentrations were seen in five dogs with leishmaniasis, as another protozoal vector-borne disease, with a significant increase if treatment was successful." (PMID 41437958, 2025).
macrosomia (2 papers, 2023 to 2025). "Pregnant women in the GDM with macrosomia group had higher gestational weight gain, weight at delivery, OGTT results, glycated hemoglobin, serum triglycerides, cystatin C, apolipoprotein A1, and lipoprotein-a compared to the control group (P < 0.05)." (PMID 40797060, 2025).
Mitral regurgitation (2 papers, 2015 to 2021). An abnormality of the mitral valve characterized by insufficiency or incompetence of the mitral valve resulting in retrograde leaking of blood through the mitral valve upon ventricular contraction. "Moreover, with ordinal logistic regression, apolipoprotein-A1 remained the only independent factor associated with mitral regurgitation." (PMID 26405438, 2015). "High-density lipoprotein, apolipoprotein-A1, haptoglobin and haptoglobin-α2 chain levels significantly decreased proportionally to the degree of mitral regurgitation when compared to controls." (PMID 26405438, 2015). "Apolipoprotein-A1 was an independent predictor of severe mitral regurgitation." (PMID 26405438, 2015).
mood disorder (2 papers, 2023 to 2025). A cognitive disorder a disturbance in which the person's mood is hypothesized to be the main underlying feature. "In addition, apolipoproteins, particularly apolipoprotein A1 (ApoA1) and apolipoprotein B (ApoB), play a role in lipid transport and inflammation implicated in mood disorders." (PMID 41220462, 2025).
nervous system cancer (2 papers, 2020 to 2024). A primary or metastatic malignant neoplasm involving the nervous system. "We observed that low levels of HDL cholesterol and apolipoprotein A1 were associated with an increased risk of several cancers, with the increased risk being most pronounced for hematological and nervous system cancer, and to a minor extent for breast and respiratory cancer." (PMID 32998735, 2020).
neuropathy (2 papers, 2015 to 2020). A disorder affecting the nervous system that manifests with pain, tingling, numbness, and/or muscle weakness. "Also, APOA1 convincingly plays a role not only in the early stage but also in late neuropathy." (PMID 26337083, 2015).
pregnancy disorder (2 papers, 2021 to 2022). A disorder that is related to pregnancy. "Moreover, APOA1 expression is dysregulated in pregnancy disorders." (PMID 34201586, 2021).
sarcopenia (2 papers, 2025 to 2026). Progressive decline in muscle mass due to aging which results in decreased functional capacity of muscles. "Compared to the stable nonsarcopenic group, individuals who developed sarcopenia demonstrated significant APOA1 (fold change -1.42, p < 0.001) and KLKB1 downregulation and LECT2 upregulation." (PMID 41782349, 2026).
Splenomegaly (2 papers, 2024 to 2025). Abnormal increased size of the spleen. "This patient exhibited lipid accumulation in the tonsils, splenomegaly, and severely reduced HDL-C (0.05 mmol/L) with undetectable ApoA1 in plasma." (PMID 40617357, 2025). "The homozygous male patient had splenomegaly, hepatosplenomegaly, a HDL cholesterol level of 0.05 mmol/l, and no detectable ApoA1 in serum, in addition to a family history of premature cardiovascular events." (PMID 38052254, 2024).
tuberculosis (2 papers, 2025). A chronic, recurrent infection caused by the bacterium Mycobacterium tuberculosis. "Furthermore, CASP8, APOA1, CP and INFG were all enriched in tuberculosis." (PMID 40083347, 2025).
ulcerative colitis (2 papers, 2010 to 2021). An inflammatory bowel disease involving the mucosal surface of the large intestine and rectum. "HNF4α variants have been associated with ulcerative colitis and with the plasma concentrations of CRP and apolipoprotein A1 (APOA1)." (PMID 21203500, 2010).
alcoholism (1 paper, 2020). "IPA also found a decrease in APOA1 concentration in both AD and alcoholism, which leads to the decrease of LPS clearance and neutralization." (PMID 33199776, 2020).
anaphylaxis (1 paper, 2022). An acute hypersensitivity reaction that occurs from exposure to an allergen. "Cross-sectional time analysis of the biomarker levels in various time intervals from the studied cohort indicated that tryptase and PGF2 levels peaked (and ApoA1 bottomed) between 60 and 100 minutes after anaphylaxis onset." (PMID 35202004, 2022). "We identified tryptase, 9α,11β-PGF2, apolipoprotein A1, and hsa-miR-451a as serological biomarkers of anaphylaxis." (PMID 35202004, 2022). "However, we previously identified potentially new candidates, demonstrating the predictive power of PGF2, cys-LTs, ApoA1, and ApoE in the diagnosis of anaphylaxis." (PMID 35202004, 2022). "Notably, PGF2 and ApoA1 were not only reproduced in our current, broader study using an independent cohort, but they also turned out to be in the top 4 classifiers of the random forest, and thereby part of the best biomarker composite model to predict anaphylaxis." (PMID 35202004, 2022).
Aortic dissection (1 paper, 2021). Aortic dissection refers to a tear in the intimal layer of the aorta causing a separation between the intima and the medial layers of the aorta. "By recruiting 30,412 individuals without aortic disease at baseline from a contemporary population, Landenhed and colleagues revealed that low apoA1 was significantly associated with incident aortic dissection during a 20-year follow-up period." (PMID 35071351, 2021).